TET1 (tet methylcytosine dioxygenase 1)
Diseases named in the same sentence as TET1 in open-access papers (continued):
Sharing a sentence is not in itself a finding about the gene and the disease.
cervical carcinoma (5 papers, 2015 to 2025). A carcinoma arising from either the exocervical squamous epithelium or the endocervical glandular epithelium. "The study found a significant reduction in TET1 transcript levels in cervical tissue samples from patients with primary cervical cancer compared with those from control patients." (PMID 40520993, 2025). "The study revealed that human papillomavirus infection disrupts the epigenetic balance of DNMT1 and TET1, leading to increased DNMT1 expression and decreased TET1 expression during cervical cancer development." (PMID 40520993, 2025). "Suppressing TET1 in cervical cancer cells led to increased invasion, cell proliferation, migration, self-renewal, and tumor formation." (PMID 40520993, 2025). "PRMT5 binds to the transcription factors Snail and NuRD complexes to form transcriptional inhibitory complexes, regulating TET1 and E‐cadherin methylation and deacetylation to promote invasion and metastasis of cervical cancer." (PMID 39823268, 2025). "Our data suggest that the PRMT5 inhibitor EPZ015666 can lead to an induction of TET1 expression and 5hmC, and inhibit the invasive potential of cervical cancer cells, making PRMT5 a potential target for cancer diagnosis and treatment." (PMID 33953349, 2021). "The PRMT5 inhibitor EPZ015666 suppressed EMT and the invasive potential of cervical cancer cells, and led to an induction of TET1 expression and 5hmC." (PMID 33953349, 2021). "Studies suggest that decreased TET1 expression may play a crucial role in the development and progression of cervical cancer." (PMID 40520993, 2025). "TET1 is emerging as a key player in the pathogenesis of cervical cancer." (PMID 40520993, 2025). "Additionally, TET1 influenced autophagy levels in cervical cancer cells by mediating the methylation of autophagy promoter regions, particularly in genes like nuclear factor-κB repressing factor (NKRF) and histone H2A type 1 (HIST1H2AK)." (PMID 40520993, 2025). "Moreover, TET1 plays a complex role in the interplay between human papillomavirus infection and cervical cancer progression." (PMID 40520993, 2025). "TET1 hypermethylation was observed in the ALL cell line SKW-3, and the cervical cancer cell line in HeLa." (PMID 25557833, 2015). "More importantly, EPZ015666 promotes the conversion of 5mC to 5hmC in cervical cancer cells, which may depend on the inhibitory effect of PRMT5 on TET1 expression." (PMID 33953349, 2021).
endometriosis (5 papers, 2018 to 2023). The growth of functional endometrial tissue in anatomic sites outside the uterine body. "The study showed a significant decrease in the expression of TET1 gene in the group of infertile endometriosis patients compared to fertile patients, however, the expression remained unchanged in idiopathic infertile patients." (PMID 37576599, 2023). "With the advancement of technology and improvement of experimental approaches, a deep understanding of the roles of TET1 in endometriosis will be possible." (PMID 32983650, 2020). "To our knowledge, we are the first to explore the relationship between EMT and the demethylation enzyme TET1 in endometriosis." (PMID 32983650, 2020). "Particular attention was paid here to the TET1 protein, which could become the target of epigenetic therapy in future research protocols in the group of infertile women with endometriosis." (PMID 35409163, 2022). "Our findings suggest that the demethylation enzyme TET1 may play a role in the EMT pathological process of endometriosis." (PMID 32983650, 2020). "Although various epigenetic mechanisms have been demonstrated to regulate EMT under hypoxia status, the role of the DNA demethylation enzyme TET1 in regulating hypoxia-induced EMT in endometriosis remains largely unknown." (PMID 32983650, 2020). "However, the function of TET1 in endometriosis is not yet fully understood." (PMID 32983650, 2020). "Besides, endometriosis lesions had more TET1 and N-cadherin co-localized cells." (PMID 32983650, 2020). "Therefore, our study demonstrates for the first time that the enhanced epithelial expression of TET1 in ectopic lesions may play a crucial role in the EMT phenotype of endometriosis while the role of TET1 in stromal cells needs to be further investigated." (PMID 32983650, 2020). "To evaluate the expression and localization of TET1 and EMT markers, E-cadherin and N-cadherin, in endometriosis, we performed IHC and immunofluorescence double staining in human endometrial tissues." (PMID 32983650, 2020). "One study investigated the TET1 gene expression in the endometrium of the group of infertile endometriosis patients, infertile non-endometriosis patients, and in the group of patients without any reproductive disturbances." (PMID 37576599, 2023). "They observed a significantly diminished level of TET1 transcripts and TET1 protein in infertile endometriosis patients compared with fertile women without this condition." (PMID 35409163, 2022). "Hypoxia induces the expression of TET1, mediated by transcription factor HIF-2α, which may promote the EMT of endometriosis." (PMID 32983650, 2020). "We hypothesized that hypoxia may increase TET1 expression, mediated by HIF-2α, thus potentially inducing the EMT of endometrial epithelial cells and contributing to the development of endometriosis." (PMID 32983650, 2020). "All in all, these data suggest that TET1 is upregulated and EMT may occur in the glandular epithelium of endometriosis." (PMID 32983650, 2020). "Ten–eleven translocation genes (TET1, TET2, and TET3) are downregulated in endometriosis." (PMID 29743986, 2018). "Along those lines, endometriosis tissues have decrease expression of ten-eleven translocation genes (TET1, TET2, and TET3), which convert 5-methylcytosine to 5-hydroxymethlcytosine and play a role in changes in levels of 5-hydroxymethylcytosine marks in endometriosis tissues and blood." (PMID 30087267, 2018). "Hypoxia induces the expression of TET1 regulated by HIF-2α, thus may promote EMT in endometriosis." (PMID 32983650, 2020).
hepatoblastoma (5 papers, 2019 to 2024). Hepatoblastoma (HB) is a malignant hepatic tumor and is the most common pediatric liver cancer. "During hepatoblastoma, a general disruption in the expression of genes from the epigenetic machinery was observed, mainly upregulation of UHRF1, TET1, and TET2, in association with an enrichment of 5 hmC content." (PMID 39684755, 2024). "In the context of hepatoblastoma, the enrichment of 5-hydroxymethylcytosine has been associated with disrupted expression of UHRF1, TET1, and TET2." (PMID 39595571, 2024). "We observed in hepatoblastomas a general disrupted expression of these genes from the epigenetic machinery, mainly UHRF1, TET1, and TET2 upregulation, in association with an enrichment of 5hmC content." (PMID 31249594, 2019).
Insulin resistance (5 papers, 2020 to 2025). Increased resistance towards insulin, that is, diminished effectiveness of insulin in reducing blood glucose levels. "In conclusion, our results demonstrate that Tet1 deficiency suppresses gluconeogenesis as well as improves glucose tolerance and insulin resistance in mice." (PMID 34738906, 2021). "(H) Homeostatic Model Assessment for Insulin Resistance (HOMA-IR) assay in HFD-fed Tet1+/- male mice and WT male mice (**p < 0.01)." (PMID 34738906, 2021). "GPER expression is strongly increased in tissues from EC patients with insulin resistance and also positively correlates with TET1 expression in EC tissues, which further indicate the role of insulin in the progression of EC mediated by TET1-driven GPER expression." (PMID 36750868, 2023).
liver cancer (5 papers, 2016 to 2024). An epithelial or non-epithelial malignant neoplasm that arises from the liver. "Among these, an enhancer within the human HMGA2 gene’s third intron mediates TET1-promoted cell growth in human liver cancer." (PMID 39335310, 2024). "Transcriptome analysis of liver cancer samples indicated that TET1 was highly expressed in liver cancer tissues, and TET1 gene knockout in liver cancer cell lines reduced hmC deposition and inhibited cell growth." (PMID 35978806, 2022). "To further investigate whether TET2 regulates cGAS expression, we overexpressed Tet1, Tet2, and Tet3 in liver cancer cells, respectively." (PMID 38177099, 2024).
non-small cell lung carcinoma (5 papers, 2020 to 2025). A group of at least three distinct histological types of lung cancer, including non-small cell squamous cell carcinoma, adenocarcinoma, and large cell carcinoma. "In non-small cell lung carcinomas, Tet1 acts as an oncogene and its knockdown leads to the induction of p21 as well as an increased senescence in cancer cells." (PMID 35456045, 2022).
renal carcinoma (5 papers, 2018 to 2025). A carcinoma arising from the epithelium of the renal parenchyma or the renal pelvis. "Fisetin treatment resulted in a significant reduction in genomic 5hmC levels within human renal cancer stem cells (HuRCSCs), accompanied by a decrease in both TET1 mRNA and protein expression." (PMID 41226811, 2025). "At the same time, we found that CD44+/CD105+ renal cancer cells have significantly higher expression of TET1 than CD44‐/CD105‐ renal cancer cells." (PMID 30411496, 2019). "Firstly, we discovered an interesting phenomenon: all pathological sections from different types of renal cancer tissues from patients showed high TET1 protein expression." (PMID 30411496, 2019). "It indicated that TET1 could be targeted and 5hmC could be a potential indicator for the treatment of fisetin in renal cancer." (PMID 34957093, 2021). "Thus, we conclude that fisetin inhibits the epigenetic mechanism in renal cancer stem cells, that is, fisetin inhibits TET1 expression and reduces 5hmC modification in specific loci in the promoters of CCNY/CDK16 in HuRSCs." (PMID 30411496, 2019). "However, endogenous TET1 expression was significantly decreased after renal cancer stem cells were treated with fisetin and this decrease is directly proportional to treatment duration." (PMID 30411496, 2019). "Fisetin, a natural flavonol, was reported to inhibit the activity of TET1, reduce 5hmC levels in CCNY/CDK16 promoter, and further restrain the invasion and progression of renal cancer stem cells." (PMID 34957093, 2021). "Our study found that renal cancer tissues and CD44+/CD105+ HuRCSCs both show high TET1 protein expression." (PMID 30411496, 2019). "HuRCSCs, identified by the CD44+/CD105+ markers, were found to exhibit significantly higher levels of both genomic 5hmC and TET1 expression compared to non-stem renal cancer cells (HuNRCCs, CD44-/CD105-)." (PMID 41226811, 2025). "Immunofluorescence staining results showed that TET1 protein is highly expressed, regardless of the type of renal cancer tissue." (PMID 30411496, 2019). "Therefore, in summary, we found that fisetin inhibits the epigenetic mechanism in renal cancer stem cells, that is, fisetin inhibits TET1 expression and reduces 5hmC modification in specific loci in the promoters of CCNY/CDK16 in renal cancer stem cells." (PMID 30411496, 2019).
adenoma (4 papers, 2013 to 2025). A neoplasm arising from the epithelium. "These genetic variations were linked to the up-regulation of genes associated with inflammation, immune responses, and interferon pathways in Tet1 and Tdg-mutant colonic adenomas, compared with control adenomas." (PMID 40520993, 2025). "Western blotting analysis was also done for TET1 and showed very low expression levels in the two analyzed PCs and low to variable expression levels in the nine analyzed adenomas." (PMID 26973719, 2016). "We previously showed that the TET1 gene is preferentially methylated in CIMP-positive and BRAF mutant CRCs and adenomas, which suggests TET1 is one of the genes affected by CIMP-related hypermethylation." (PMID 27977763, 2016). "Notably, Tet1-mutant adenomas displayed hypermethylation of CpG islands." (PMID 40520993, 2025).
B-cell acute lymphoblastic leukemia (4 papers, 2017 to 2025). A neoplasm of lymphoblasts committed to the B-cell lineage, typically composed of small to medium-sized blast cells. "Recently, Chen et al54 uncovered a carcinogenic role for phosphorylated TET1 in B-cell acute lymphoblastic leukemia, driven by protein kinase C epsilon (PRKCE) and ataxia-telangiectasia mutated (ATM) kinases." (PMID 40520993, 2025). "In humans, TET1 and TET2 have been previously shown to be concomitantly downregulated in B cell acute lymphoblastic leukemia and to have overlapping functions in B cell development and leukemogenesis." (PMID 29029465, 2017).
brain tumor (4 papers, 2017 to 2025). "A study in brain tumor cells suggested that downregulation of TET1 led to a significant reduction of STAT3 in transcript level." (PMID 36658614, 2023). "Further studies should evaluate functional significance of increased levels of TET1 and 5caC in medulloblastoma and ependymoma providing new information on the pathogenesis and potentially leading to development of novel targets for therapy of these brain tumours." (PMID 28228863, 2017). "In contrast, expression of TET2 and TET1 was generally higher (e.g. 2.37-fold for BXD-1425EPN and 4.14-fold for DKFZ-EP1NS cells for TET2) in the brain tumour cell lines compared with HeLa cells." (PMID 28228863, 2017). "To get an insight into potential molecular mechanisms for the 5caC enrichment in medulloblastoma and ependymoma cells, we examined the levels of TET1/2/3 and TDG transcripts in the four paediatric brain tumour cell lines and HeLa cells." (PMID 28228863, 2017).
chronic lymphocytic leukemia (4 papers, 2017 to 2023). "Loss of TET1 expression due to DAC treatment has also been found in chronic lymphocytic leukemia cells and can be at least partially responsible for DAC-induced hypermethylation." (PMID 36278182, 2022).
clear cell renal cell carcinoma (4 papers, 2017 to 2021). "For example, in renal clear cell carcinoma, the expressions of TET1, TET3, and TDG are positively correlated with that of hsa-miR-21-5p." (PMID 32637580, 2020). "Correspondingly, expression of TET1, which catalyzes the formation of 5hmC, was also lower in grade III renal clear cell carcinomas than in grade I or II disease." (PMID 28969028, 2017).
Cognitive impairment (4 papers, 2022 to 2025). Abnormal cognition is characterized by deficits in thinking, reasoning, or remembering. "Based on our current data in combination with existing literatures, it is plausible that TET1 protein deficiency and demethylation disorders of the Bcl2 promotor likely contribute to a potential mechanism underlying fluoride elicited cognitive disorders." (PMID 40133886, 2025). "To further investigate the biological function of TET1 in prenatal fluoride-induced cognitive impairment, we examined the morphological changes of hippocampus in NaF and Tet1 deficient male mice using Nissl-staining, Golgi staining, and analyses of cell density and cytoarchitecture." (PMID 40133886, 2025). "Our results indicated that exposure to a high sodium fluoride (100 mg/L) during pregnancy in the mouse can cause the cognitive deficits of their offspring, accompanied by a decrease in the expression of Tet-eleven translocation protein 1 (TET1), an enzyme responsible for DNA hydroxymethylation." (PMID 40133886, 2025). "Consequently, the TET1 enzyme is essential for proper brain function, and mutations or variations in TET1 expression may be implicated in, or even primarily responsible for, cognitive deficits in mammals." (PMID 40133886, 2025). "Our results indicate that TET1 mitigates prenatal fluoride-induced cognitive impairment, at least in part, by modulating Bcl2 DNA hydroxymethylation and the consequently reducing neuron apoptosis." (PMID 40133886, 2025). "Intriguingly, Tet1 knock-out mice exhibited cognitive deficits similar to those observed in male animals exposed to high levels of fluoride." (PMID 40133886, 2025). "Intriguingly, Tet1 knockout mice also showed an identical abnormality in hippocampal morphology and cytoarchitecture responsible for the spatial learning and memory, resulting in cognitive deficits." (PMID 40133886, 2025). "Furthermore, TET1 presents a promising therapeutic target for addressing cognitive impairment induced by prenatal sodium fluoride exposure." (PMID 40133886, 2025). "Conversely, enzymes that facilitate gene transcription and chromatin accessibility, such as Tet1/2, Kat7, and Cbp, were downregulated following binge-like alcohol exposure, consistent with previous reports linking alcohol consumption to chromatin condensation and cognitive impairments." (PMID 41561438, 2025). "A study validating the functional role of TET1 in adult neurogenesis showed that Tet1-knockout mice had significant defects in the maintenance of short-term memory and learning delay, indicative of cognitive impairment, together with a significant decrease in the number of NPC cells." (PMID 36142283, 2022).
developmental delay (4 papers, 2018 to 2023). "However, Tet1 or Tet2 -null mice are viable and overtly normal double Tet1/Tet2-deficient mice are also obtained, but, some Tet1-deficient mice display a smaller body size at birth, which might reflect a developmental delay." (PMID 33834024, 2021). "This expands on our prior work by demonstrating that the non-catalytic functions of Tet1 are essential for preventing developmental delay." (PMID 35150568, 2022).
diabetes (4 papers, 2018 to 2024). "This does not support any association of diabetes or the DNA 5hmC amount with the expression level of TET1 mRNA." (PMID 30574144, 2018). "These factors may cause the increase of TET1 and decrease of TET3 expression levels, which become possible intervention points for the prevention and treatment of diabetes and its complications." (PMID 30574144, 2018). "The expression of TET3 (but not TET1 and TET2) mRNA was significantly increased in skeletal muscle tissues of humans with diabetes as compared with non-diabetic control counterparts." (PMID 38216792, 2024). "Here, we compared the mRNA and protein levels of TET1, TET2, and TET3 in non-diabetic (ND) control subjects, patients with only type 2 diabetes only (D), and patients with diabetes peripheral artery disease (D-PAD)." (PMID 30574144, 2018).
gastric tumors (4 papers, 2015 to 2022). "Here we reveal that a decrease in 5hmC level is common in gastric tumors, is strongly associated with decreased expression of TET1, and is significantly associated with poor survival of patients with GC." (PMID 26462176, 2015). "A recent study found that miR-4284 could promote gastric tumor cell growth, migration and invasion by directly targeting TET1." (PMID 34557357, 2021). "Herein, we found that TET1 expression and 5-hmC content were low in gastric tumors compared to its adjacent non-tumor tissues." (PMID 27121319, 2016). "Methyl-CpG Binding Domain Sequencing and Reduced Representation Bisulfite Sequencing identified unique CpG methylation signatures at the CpG island 3′-shore region located 1.3 kb from the transcription start site of TET1 in gastric tumor cells but not in normal mucosa." (PMID 26462176, 2015).